ENSG00000287319 (novel transcript, antisense to SERPINI1)
Gene: Long non-coding RNA gene on chromosome 3 (167,794,947 to 167,811,081, reverse strand). Ensembl gene ENSG00000287319.
Gene Ontology:
Biological process: miRNA-mediated post-transcriptional gene silencing